S1PR2 (sphingosine-1-phosphate receptor 2)
Diseases named in the same sentence as S1PR2 in open-access papers (continued):
Sharing a sentence is not in itself a finding about the gene and the disease.
Osteopenia (2 papers, 2019 to 2024). Osteopenia is a term to define bone density that is not normal but also not as low as osteoporosis. "Moreover, since S1pr2-deficient mice, similar to S1pr3-deficient mice were found to display osteopenia, it might be informative to combine the S1P2-deficiency with mouse models of increased S1P levels (including Sgpl1-deficient mice) in future experiments." (PMID 31314788, 2019). "We have also identified S1PR2 as an important mediator of the autonomous osteoanabolic effects of S1P in OBs and demonstrated that a pharmacological S1PR2 agonist protects against ovariectomy-induced osteopenia." (PMID 38477738, 2024). "S1PR2 regulates the expression of Osterix (Sp7), a key transcription factor in osteoblastogenesis resulting in osteopenia in S1PR2 knockout mice." (PMID 38477738, 2024).
osteopetrosis (2 papers, 2017 to 2025). Osteopetrosis, also known as marble bone disease, is a descriptive term that refers to a group of rare, heritable disorders of the skeleton characterized by increased bone density on radiographs. "S1PR2−/− mice showed higher bone density accompanied by decrease in osteoclastic bone resorption thus showing overall moderate osteopetrosis as compared to control littermates." (PMID 28524744, 2017). "A rationale for S1PR2 as a therapeutic target can be derived from the observation that S1PR2 knockout mice develop osteopetrosis." (PMID 28524744, 2017).
pancreatitis (2 papers, 2022 to 2024). Inflammation of the pancreas. "Western blot analysis showed that S1PR2 was markedly increased at 12 h in the pancreas of taurocholate pancreatitis model mice compared to the control." (PMID 36229875, 2022). "Pharmacologic inhibition of S1PR2 signaling by JTE-013 or knockdown of S1PR2 expression using a gene-specific shRNA alleviated pancreatic injury and resulted in lower inflammatory responses in caerulein pancreatitis mouse models." (PMID 36229875, 2022). "To examine whether S1PR2 is responsible for inflammatory response within acinar cells during the early phase of pancreatitis, we treated cells with JTE-013 (an antagonist of S1PR2) or S1PR2-shRNA to block the effects." (PMID 36229875, 2022).
preeclampsia (2 papers, 2016 to 2020). Preeclampsia is a hypertensive disorder of pregnancy that is characterized by new-onset hypertension with proteinuria presenting after 20 weeks of gestation, and depending on mild or severe forms may initially present with severe headache, visual disturbances, and hyperreflexia. "Thus, the inverse regulation of S1PR1 and S1PR2 expression in chorionic arteries might explain, at least in part, the vascular dysfunction reported in preeclampsia, including a heightened placental vascular resistance." (PMID 32033121, 2020).
pulmonary arterial hypertension (2 papers, 2021 to 2025). Pulmonary arterial hypertension (PAH) is a group of diseases characterized by mean pulmonary artery pressure >20 mmHg and elevated pulmonary arterial resistance leading to right heart failure. "In pulmonary arterial hypertension (PAH), S1PR2-mediated signaling drives excessive SMC proliferation and vascular remodeling, processes that elevate vascular resistance and arterial pressure." (PMID 41511294, 2025).
viral infection (2 papers, 2012 to 2019). "When a vaccinia virus infects mice, skin mast cells protect the mice against viral infection by triggering mast cell receptor S1PR2 expression and by releasing AMPs into the mucosa against pathogen infections." (PMID 23226256, 2012). "For example, S1PR2 affects mast cell triggering during viral infection." (PMID 31546702, 2019).
abdominal aortic aneurysm (1 paper, 2022). Enlargement and ballooning of the vessel that supplies arterial blood to the abdomen, pelvis and legs. "In the abdominal aortic aneurysm, it was shown that the level of S1PR2 decreases, while the amount of S1PR3 increases compared to the control tissue." (PMID 35745168, 2022). "Therefore, the reduced expression of anti-inflammatory S1PR2 in abdominal aortic aneurysm vascular smooth muscle cells may impede prostacyclin synthesis and, as a result, lead to severe inflammatory reaction in AAA." (PMID 35745168, 2022).
alcoholic liver diseases (1 paper, 2025). A disorder caused by damage to the liver parenchyma due to alcohol consumption. "Furthermore, the activation of S1PR2 can enhance the secretion of proinflammatory factors via the mitogen-activated protein kinase (MAPK) and NF-kB pathways, whereas inhibition of S1PR2 can alleviate inflammatory damage associated with alcoholic liver disease." (PMID 40807240, 2025).
Arthritis (1 paper, 2024). Inflammation of a joint. "CIA causes increases in arthritis scores, foot swelling, synovial hyperplasia, pannus formation, proteoglycan depletion, cartilage damage, and bone erosion, but these effects are markedly reduced when JTE-013 is administered to S1pr2 WT mice." (PMID 39769163, 2024).
brain-tumor (1 paper, 2023). "S1PR1, S1PR2 and S1PR3 were shown to be elevated in patient brain-tumor samples compared to normal brain samples, and Kaplan–Meier analyses have demonstrated an association between S1PR1 and S1PR2 with patients’ survival times." (PMID 37686550, 2023).
cholestatic jaundice (1 paper, 2024). "Notably, levels of the DCA in the sera of patients with cholestatic jaundice are sufficient to activate S1PR2 in vitro." (PMID 39664579, 2024).
classical Hodgkin lymphoma (1 paper, 2024). "For example, in the Hodgkin/Reed–Sternberg (HRS) cells of classical Hodgkin lymphoma (cHL), S1P has been shown to activate phosphatidylinositide 3-kinase (PI3-K) signaling, an effect that is mediated by the increased expression of S1PR1 and the decreased expression of S1PR2." (PMID 38339325, 2024).
clonorchiasis (1 paper, 2022). Infection of the biliary passages with clonorchis sinensis, also called Opisthorchis sinensis. "This study supports S1PR2 as a potentially new therapeutic target for treating clonorchiasis." (PMID 36339341, 2022).
coronary artery disease (1 paper, 2020). "Several animal models have already indicated that inhibition of S1PR2 could be a valuable pharmaceutical target for vascular recovery in coronary artery disease and stroke." (PMID 33339817, 2020). "The associations that we report here represent the first direct human data supporting that S1PR2 might play an important role in ischemic heart disease." (PMID 33339817, 2020).
COVID-19 (1 paper, 2023). A disease caused by infection with severe acute respiratory syndrome coronavirus 2. "Expression of S1PR2 was more robust in the squamous metaplasia in the COVID-19+ autopsies." (PMID 37868972, 2023). "Interestingly, in COVID-19 convalescents, macrophage like cells in the alveolar lining were S1PR2+." (PMID 37868972, 2023). "Our evaluations of S1PR1 and S1PR2 suggest that the SK1 induction and downstream signaling may have involved S1PR2 in COVID-19+ autopsies and not S1PR1." (PMID 37868972, 2023).
diabetic nephropathy (1 paper, 2013). "For example, S1PR3 is related to fibrosis in cardiac ventricular fibroblasts, S1PR2 is involved in a diabetic nephropathy model, and a relationship has been found between S1PR3 and fibrosis in myofibroblasts." (PMID 24744854, 2013).
endotoxemia (1 paper, 2018). "Zhang and colleagues characterized S1PR2 as a novel regulator of vascular inflammation that is critical in endothelial responses to injury during endotoxemia." (PMID 29854830, 2018).
epilepsy (1 paper, 2020). A brain disorder characterized by episodes of abnormally increased neuronal discharge resulting in transient episodes of sensory or motor neurological dysfunction, or psychic dysfunction. "In the future, we will perform experiments in different animal species and animal seizure models, and further to investigate the effect of SphK1/S1PR2 signal specific inhibitor and agonists on molecules associated with epilepsy." (PMID 33134289, 2020). "Therefore, depending on the brain region, species, and epilepsy phase, subcellular localization of S1PR2 might be different, a hypothesis that remains to be proved in the future." (PMID 33134289, 2020).
glaucoma (1 paper, 2018). Increased pressure in the eyeball due to obstruction of the outflow of aqueous humor. "S1PR2′s presence in the outflow pathway follows logically from past studies on S1P receptor antagonist drugs and S1PR2 specific agonists and has great implications for understanding and treating conditions that include elevated IOP in glaucoma." (PMID 30563056, 2018).
graft versus host disease (1 paper, 2025). An immune system disorder that occurs after allogeneic hematopoietic stem cell transplant and is a reaction of donor immune cells against host tissues. "Multiplex immunohistochemistry revealed increased numbers of S1PR2+CD45+CD68+FCN1+ inflammatory macrophages and S1PR2+CD45+CD68+MARCO+ Kupffer cells in liver tissues showing ductopenia due to graft-versus-host disease and rejection post-liver transplant compared with normal liver." (PMID 39854311, 2025).
Hematochezia (1 paper, 2018). The passage of fresh (red) blood per anus, usually in or with stools. "The results showed that S1PR2 blockage significantly reduced the body weight loss and colon length shortening, exhibiting much lower MPO activity and hematochezia score, meanwhile ameliorating mucosal inflammatory cell infiltration and mucosal epithelium disruption." (PMID 29854830, 2018).
IgA nephropathy (1 paper, 2022). "Treatment of HIGA mice with JTE013, a S1PR2 antagonist, rescued them from proteinuria, indicating a major role for S1P in the development of IgA nephropathy, possibly mediated by S1PR2." (PMID 35457062, 2022). "It was demonstrated that S1P bound to APOM is protective against IgA nephropathy by suppressing the downstream signaling of S1PR1 and S1PR3, whereas S1P bound to albumin showed deteriorating effects through S1PR2." (PMID 35457062, 2022).
impetigo (1 paper, 2024). A pyoderma consisting of three forms of skin lesions having either a thick, adherent, recurrent, dirty yellow crust with an erythematous margin (common or superficial impetigo) or lessions which are superficial, thin-walled, and bullous as found in bullous impetigo. "Higher expression levels of S1PR1 and S1PR2 observed in the skin of impetigo patients and changes in the distribution patterns of these receptors were also aligned with these findings." (PMID 38862781, 2024).
inflammatory skin disease (1 paper, 2023). Inflammatory skin disorders covers a broad category that includes many conditions ranging in severity, from mild itching to grave medical health complications These disorders are common in people of all ages and races. "Particularly, subtype-specific agonists and antagonists help to further understand the complex role of S1P signaling, and it seems promising to further elucidate these roles, especially the role of S1PR2 and S1PR3 in inflammatory skin diseases and itch." (PMID 36674974, 2023).
interstitial lung disease (1 paper, 2022). A diverse group of lung diseases that affect the lung parenchyma. "Notably, the majority of patients with positive S1PR2-aAb (60.7%) or S1PR3-aAb (71.9%) displayed interstitial lung disease." (PMID 35860272, 2022).
intracerebral haemorrhage (1 paper, 2015). "To study the role of S1PR2 in the development of intracerebral haemorrhage after I/R injury, we used a model of spontaneous haemorrhagic transformation." (PMID 26243335, 2015). "In addition, acute inhibition of S1PR2 by oral administration of JTE013, 10 min after reperfusion, dramatically inhibited the development of intracerebral haemorrhage (ipsilateral/contralateral ratio 1.04±0.05)." (PMID 26243335, 2015).
kidney damage (1 paper, 2020). "The FTY720 does not act on S1PR2, whereas the S1PR2-mediated signaling has been shown to play a very important role in the kidney damage." (PMID 32393187, 2020).
leiomyoma (1 paper, 2022). A well-circumscribed benign smooth muscle neoplasm characterized by the presence of spindle cells with cigar-shaped nuclei, interlacing fascicles, and a whorled pattern. "Similarly, S1PR2, S1PR3, and S1PR5 mRNA levels were significantly higher in uterine fibroids in comparison with myometrial healthy tissues; both S1PR2 and S1PR3 protein levels were also elevated in the leiomyoma." (PMID 36362323, 2022).
leishmaniasis (1 paper, 2018). Infectious disease that is transmitted through the bite of hematophagous female phlebotomine sand flies. "In summary, we showed that S1P signaling plays a protective role in Leishmania infection and S1PR2-3 can be considered as novel and attractive therapeutic target against leishmaniasis." (PMID 30118478, 2018).
liver cancer (1 paper, 2018). An epithelial or non-epithelial malignant neoplasm that arises from the liver. "Recently, S1P/S1PR2 has been shown to activate YAP, a major oncogenic driver in liver cancer." (PMID 29643998, 2018).
liver failure (1 paper, 2017). A liver disease characterized by the liver losing or has lost all of its function. "Taken together with previous studies, these findings support the hypothesis that following liver failure, bile acids are elevated in the circulation, gain entry into the brain and bind S1PR2 on neurons, which secrete CCL2 and lead to the activation of microglia." (PMID 28725183, 2017).
malaria (1 paper, 2022). Malaria is a serious and sometimes fatal disease caused by a parasite that commonly infects a certain type of mosquito which feeds on humans. "The present study indicated that liver tissue from malaria-infected mice has decreased expression of S1PR1, S1PR2, and S1PR3 and increased expression of SphK1." (PMID 35333897, 2022).
meningococcal infection (1 paper, 2023). Infections with bacteria of the species neisseria meningitidis. "Importantly, N. meningitidis induced increased expression of S1PR2 in BECs, suggesting a shift in the S1PR expression pattern on hCMEC/D3 cells after meningococcal infection towards S1PR2-mediated signaling that is crucial for barrier disruption." (PMID 38033162, 2023).
metabolic syndrome (1 paper, 2025). A cluster of metabolic risk factors for CARDIOVASCULAR DISEASES and TYPE 2 DIABETES MELLITUS. "No BS for either KLF14 or SREBF1 was identified in the promoters of MC4R, 5-HT2C, MC3R, S1PR2, FFAR1/GPR40, and HCR2 within this database, despite their known association with metabolic syndrome." (PMID 40243421, 2025).
pancreatic disorders (1 paper, 2024). "Similarly, the compound JTE-013 serves as a specific antagonist targeting S1PR2, and is frequently employed to investigate the functional roles of S1PR2 in diverse pancreatic disorders." (PMID 39519028, 2024).
periodontitis (1 paper, 2023). An acute or chronic inflammatory process that affects the tissues that surround and support the teeth. "Because treatment with JTE013 inhibited inflammation, attenuated osteoclastogenesis, promoted angiogenesis, and induced bone healing, inhibition of S1PR2 by JTE013 may potentially serve as a therapeutic strategy to treat inflammatory bone loss diseases, including periodontitis." (PMID 36834810, 2023). "In this study, using a ligature-induced, periodontitis model, we aimed to determine if inhibiting S1PR2 by JTE013 could increase gene expression for the growth factors (VEGF, GDF15, and PDGF), enhance angiogenesis, and promote alveolar bone regeneration following inflammatory bone loss." (PMID 36834810, 2023).
peripheral artery disease (1 paper, 2022). "This research provides a novel strategy for EC-target knockdown of S1pr2 as a new therapeutic intervention for patients with peripheral artery disease." (PMID 35836816, 2022). "This study provides a future promising EC-target therapy for peripheral arterial disease through the S1pr2 signal pathway." (PMID 35836816, 2022). "However, the cell-specific effect of S1pr2 on post-ischemic angiogenesis and revascularization in peripheral arterial disease is not well known." (PMID 35836816, 2022). "This EC-target knockdown of S1pr2 treatment significantly improved post-ischemic angiogenesis and blood flow reperfusion, thereby providing a novel cell-target strategy for patients with peripheral artery disease." (PMID 35836816, 2022). "This EC-targeted strategy to dampen S1pr2 significantly enhanced post-ischemic angiogenesis and boosted blood perfusion after HLI, supplying a novel therapy target for patients with peripheral arterial disease." (PMID 35836816, 2022).
retinal diseases (1 paper, 2023). "Together, these results suggest that S1PR2 plays an important role in the light responses of the retina and provides a useful target for the future development of novel therapeutics to treat and/or prevent different retinal diseases." (PMID 38136563, 2023).
rheumatoid arthritis (1 paper, 2024). A chronic, systemic autoimmune disorder characterized by inflammation in the synovial membranes and articular surfaces. "Our study aims to determine whether inhibiting S1P2 can mitigate collagen-induced rheumatoid arthritis (CIA) by using an S1P2 antagonist, JTE-013, alongside DBA-1J S1pr2 wild-type (WT) and knock-out (KO) mice." (PMID 39769163, 2024).
transient cerebral ischaemia (1 paper, 2015). "We found that genetic deletion or pharmacological inhibition of S1PR2 promoted cerebrovascular integrity in a mouse model of transient cerebral ischaemia (tMCAO), resulting in decreased neuronal death and improved neurological scores." (PMID 26243335, 2015). "Using a mouse model of focal transient cerebral ischaemia, the middle cerebral artery occlusion model (MCAO), we report the critical role of S1PR2 in the disruption of cerebrovascular integrity after I/R injury." (PMID 26243335, 2015).
tubulovillous adenoma (1 paper, 2020). An epithelial neoplasm morphologically characterized by the presence of a villous and a tubular architectural pattern. "To validate this feature in humans, we analyzed S1PR2 expression in 5 human tubulovillous adenomas with moderate focal dysplasia, which is considered as an early precancerous lesion." (PMID 33225975, 2020).
vitamin D deficiency (1 paper, 2017). A nutritional condition produced by a deficiency of VITAMIN D in the diet, insufficient production of vitamin D in the skin, inadequate absorption of vitamin D from the diet, or abnormal conversion of vitamin D to its bioactive metabolites. "Importantly, expression of S1PR2, and therefore S1P function, can be down-regulated by vitamin D. Our data suggest that vitamin D deficiency, which is known to be associated with PE, may contribute to the impaired trophoblast migration that underlies this condition." (PMID 29208234, 2017).